FAM135B (family with sequence similarity 135 member B)
Synonyms: C8orfK32
Tractability: No criterion of Open Targets' tractability assessment is met for any kind of drug.
Gene: Protein-coding gene on chromosome 8 (138,130,023 to 138,497,261, reverse strand). Ensembl gene ENSG00000147724.
Subcellular location (Human Protein Atlas): Nuclear membrane; Nucleoplasm
Gene Ontology:
Molecular function: protein binding
Biological process: lipid metabolic process
Genetic constraint (gnomAD): Loss-of-function variants: 34 observed, 101.86 expected, observed/expected ratio (o/e) 0.33, 90% interval 0.25 to 0.44. The upper end of that interval is the gene's LOEUF score, 0.44, which puts it in group 1 of 6, group 1 being the genes least tolerant of losing a copy. Missense variants: 1,300 observed, 1,469 expected, observed/expected ratio (o/e) 0.88, 90% interval 0.85 to 0.93. Synonymous variants: 556 observed, 580.56 expected, observed/expected ratio (o/e) 0.96, 90% interval 0.89 to 1.03.
Homologues: Orthologues: chimpanzee FAM135B (99% identical), macaque FAM135B (98% identical), dog FAM135B (84% identical), rabbit FAM135B (82% identical), mouse Fam135b (81% identical), rat Fam135b (81% identical), pig FAM135B (80% identical), tropical clawed frog FAM135B (52% identical), zebrafish FAM135B (49% identical), Drosophila melanogaster CG32333 (29% identical), Caenorhabditis elegans C09D4.4 (15% identical). Paralogues in human: FAM135A (39% identical).
Diseases named in the same sentence as FAM135B in open-access papers:
FAM135B is named in the same sentence as 16 diseases in open-access papers, as found by Europe PMC text mining. Sharing a sentence is not in itself a finding about the gene and the disease. The quoted sentences say what the papers report.
esophageal squamous cell carcinoma (4 papers, 2020 to 2023). Esophageal squamous cell carcinoma (ESCC) is a type of esophageal carcinoma (EC) that can affect any part of the esophagus, but is usually located in the upper or middle third. "Mutation frequencies for FAM135B, which is associated with cellular lipid metabolic processes, are high in many different malignancies (including esophageal squamous cell cancer and small cell lung cancer)." (PMID 32639949, 2020). "It has been shown to increase progression of esophageal squamous cell carcinoma (ESCC), and mutation of FAM135B in ESCC corelated to poor prognosis." (PMID 37559138, 2023). "In a previous study, our group first identified that FAM135B is a potential driver gene of oesophageal squamous cell carcinoma (ESCC) and is frequently mutated and amplified in ESCC patients." (PMID 35979619, 2022). "Esophageal squamous cell carcinoma has been shown to strongly express FAM135B with poor prognosis and silencing FAM135B increases radiosensitivity, but there is little evidence to support mutation as the underlying cause of elevated expression." (PMID 36685819, 2022).
Esophageal Carcinoma (2 papers, 2022 to 2025). A primary or metastatic malignant neoplasm involving the esophagus.
autism (1 paper, 2013). Persistent deficits in social interaction and communication and interaction as well as a markedly restricted repertoire of activity and interest as well as repetitive patterns of behavior. "Using this method we identified associations with SNPs at the P<10−4 level in or near several genes previously implicated in autism: NLGN4X, RAPGEF4, RORA, FAM135B and CNTNAP2." (PMID 24204716, 2013).
colon cancer (1 paper, 2022). "Furthermore, we discovered that the gene FAM135B, which had not previously been described in colon cancer, was down-regulated and served as a prognostic factor for COAD." (PMID 35610288, 2022).
muscular atrophy (1 paper, 2023). The loss of muscle tissue due to inactivity or disease. "Knockdown of FAM135B in iPSC lines reduces spinal motor neuron survival and contributes to neurite defects as seen in spinal and bulbar muscular atrophy." (PMID 36918541, 2023).
myopia (1 paper, 2025). "TENM3 had been associated with myopia in adults before, whilst the other three loci, MIR4275, LOC101928911 and FAM135B, were novel." (PMID 40410244, 2025).
pulmonary tuberculosis (1 paper, 2011). A bacterial infection that affects the lungs and is caused by Mycobacterium tuberculosis. "Two SNPs were significantly associated with extrapulmonary vs. pulmonary tuberculosis, one of which was in a known gene FAM135B (family with sequence similarity 135, member B)." (PMID 21281516, 2011).
tuberculosis (1 paper, 2011). A chronic, recurrent infection caused by the bacterium Mycobacterium tuberculosis. "The gene FAM135B located on chromosome 8 and is a protein coding gene that is expressed in several tissues/organs such as the brain and heart, but has not previously been linked to either form of tuberculosis." (PMID 21281516, 2011).
cancer (12 papers, 2014 to 2025). A tumor composed of atypical neoplastic, often pleomorphic cells that invade other tissues. "Through comprehensive genomic analysis of 158 ESCC cases, FAM135B was identified as a novel cancer-implicated gene that promoted malignancy of ESCC cells." (PMID 28169357, 2017). "Once cancer cells suffer DNA damage, FAM135B is released from TIP60, and the functioning pre‐assembled TIP60‐ATM complex participates in DDR." (PMID 35979619, 2022). "Of note, FAM135B has been characterized as a novel cancer gene that promotes malignancy of SCC cells." (PMID 25593196, 2015). "We identified a novel DDR regulator FAM135B which could protect cancer cells from genotoxic stress in vitro and in vivo." (PMID 35979619, 2022). ": We characterised FAM135B as a novel DDR regulator and further elucidated the role of the TIP60‐ATM axis in response to DNA damage, which suggests that targeting FAM135B in combination with radiation therapy or chemotherapy could be a potentially effective approach for cancer treatment." (PMID 35979619, 2022). "In the iC3 subtype, which was associated with the most aggressive SKCM cases, FAM135B gene mutation frequencies were increased, while CD8A, GBP5, KIAA0040, and SAMHD1 expression were downregulated, suggesting that these genes play important roles in cancer development and immune responses." (PMID 32639949, 2020). "However, the mechanism by which FAM135B modulates cancer development and progression remains unclear." (PMID 32639949, 2020). "In the case of FAM135B, FEV, CBFB, and CTNND2, the regulatory status inferred here is at odds with their documented cancer role, thereby indicating potential anomalous regulation whose resolution would be tractable to experimental investigation." (PMID 39484215, 2024). "This duplication also recurrently affected known cancer census genes such as CSMD3, COX6C, EXT1, FAM135B, MYC, and NDRG1 in SG1 and SG3 in more than 75% of patients." (PMID 36129940, 2022).
tumor (5 papers, 2015 to 2025). "Our study demonstrated that tumour cells with a high level of FAM135B acquired resistance to chemotherapy and IR‐induced DNA damage." (PMID 35979619, 2022). "FAM135B knock‐down is shown to reduce the growth, colony formation, migration and invasion ability of tumours." (PMID 35979619, 2022). "Interestingly, our preliminary study demonstrated that FAM135B was located both in the nucleus and cytoplasm, and its overexpression protected tumour cells from agent and γ‐irradiation (IR)‐induced DNA damage, confirming its roles in DDR." (PMID 35979619, 2022). "Moreover, some of the candidate genes, such as TRIB3, KRT80, and FAM135B, were found to be correlated with tumor stage or survival outcomes, implying that these candidate genes could serve as promising prognostic biomarkers for COAD patients." (PMID 35610288, 2022). "As FAM135B is a gene with unknown functions, our team then conducted in‐depth research on its function and underlying molecular mechanisms and reported, for the first time, that FAM135B promotes tumour initiation and progression through the GRN/AKT/mTOR pathway." (PMID 35979619, 2022). "Cox regression analysis demonstrated that tumor stage, STMN4 and FAM135B dysregulation were independent prognostic factors for COAD survival outcomes." (PMID 35610288, 2022). "By identifying the role of FAM135B in DDR, this suggests that the expression of FAM135B in tumours may be a key in predicting patient responses to chemotherapy and radiation therapy." (PMID 35979619, 2022).
FAM135B also shares sentences with these, for which no sentence is quoted: extrapulmonary tuberculosis (1 paper); lung squamous cell carcinoma (1); mental illness (1); ovarian carcinoma (1); refractive error (1); small cell lung carcinoma (1).